CD68 (CD68 molecule)
Diseases named in the same sentence as CD68 in open-access papers (continued):
Sharing a sentence is not in itself a finding about the gene and the disease.
Stroke (continued). "To identify changes in microglia and MDM activation in the brains of Adrb2cKO mice, we once again immunostained for CD68 3 days after stroke." (PMID 31138227, 2019). "Similar to our observations of CD68+ cells, individual Iba1+ cells in stroke cortex of clenbuterol-treated mice appeared hypertrophic." (PMID 31138227, 2019). "Microglia/macrophage activation peaked on day 7 post-stroke in the ischemic cortex, when the core area was filled with Iba1+ cells (a marker for all microglia/macrophages) and CD68+ cells having a phagocytic/macrophage-type morphology (Fa)." (PMID 29766045, 2018). "In contrast, the increase in iNOS+CD68+ cells showed a delayed profile with a very modest increase before 48 h after stroke, but increasing substantially between days 2 and 4 after stroke." (PMID 29342151, 2018). "According to the literature, Iba-1/CD45-positive macrophages expressing active phagocytosis marker CD68 facilitate the brain recovery process following stroke." (PMID 29527155, 2018). "Iba1+ cells with activated morphology were evident in the ipsilateral thalamus at day 7 post-stroke, but only a few cells were CD68+ (Fd)." (PMID 29766045, 2018). "At day 2 post-stroke, microglia/macrophage activation was observed mainly in the peri-infarct region, and few phagocytic CD68+ cells (a marker for activated, phagocytic microglia/macrophages) were present." (PMID 29766045, 2018). "On the other hand, Arg1+CD8+CD68+ cells increased until day 3 but declined thereafter and proportion wise, iNOS+CD8+CD68+ cells became the most dominant CD8+CD68+ cell type at day 4 after stroke." (PMID 29342151, 2018). "By quantitative immunohistochemistry, we further showed a gradual increase in activated CD68+ cells between 6 hours and 4 days following stroke that corroborated with increased transcripts of a general macrophage marker, Mac-1 (P < 0.001)." (PMID 29342151, 2018). "As a marker of macrophage and microglia, CD68 expression represents the evolution of inflammatory response post-stroke." (PMID 27910074, 2017). "CD68+ cells were observed at these areas on post-stroke day 5 and 7 and some of them expressed Iba1." (PMID 26952098, 2016). "In this study, we determined that bone fracture 6 hours before stroke increased CD68+ macrophages, the levels of IL-1ß and IL-6 in the peri-infarct region, which was accompanied by increased neuronal death and behavior dysfunction." (PMID 27089041, 2016). "In contrast to the recent stroke, investigation of the older stroke area revealed low number and levels of CD68-positive cells still present around the ischemic area (compare middle “recent stroke area” with “old stroke area” rows)." (PMID 27566702, 2016). "On post-stroke day 3, CD68+ cells were only rarely observed within the ischemic core and the peri-ischemic areas." (PMID 26952098, 2016). "According to the literature, Iba-1/CD45-positive macrophages expressing active phagocytosis marker CD68 facilitate brain recovery process following LPS-induced brain injury and stroke and mediate neuroprotection in Alzheimer’s disease." (PMID 27829437, 2016). "We found that bone fracture 6 hours before stroke increased the number of CD68+ cells in the peri-infarct regions (33.4±7.62% of total DAPI positive nuclei) compared to the stroke-only group (21.80±4.27%, p = 0.004)." (PMID 27089041, 2016). "U-IGF1R+ hDSCs treatment showed significantly fewer CD68+ cells infiltration at the peri-infarct area at 3 days after stroke than that of F-IGF1R+ hDSCs and control rats." (PMID 27586516, 2016). "To analyze if bone fracture before stroke increases neuroinflammation, we quantified CD68+ cells in the peri-infarct cortex." (PMID 27089041, 2016). "Double staining for the markers confirm the absence/low levels of these active caspases in remaining CD68-positive cells (compare middle “recent stroke area” with “old stroke area” rows)." (PMID 27566702, 2016).
Stroke (continued). "In fact, confocal imaging demonstrated the presence of both cleaved caspase-8 and cleaved caspase-3 in the cytoplasm of CD68-positive cells, confirming the activation for those caspases in the MMs upon stroke." (PMID 27566702, 2016). "This prompted us to analyze in greater detail the expression levels of well-defined pro-inflammatory mediators during stroke, namely interleukin-6 (IL-6), CD68, CCL3 (MIP1α), and CCL5 (RANTES) by means of rt-PCR." (PMID 24024100, 2013). "It has been well established in stroke models that until 72 h after the insult, macrophages represent only a small minority of CD68 positive cells." (PMID 22647642, 2012). "In contrast, the increased CD-68 expression post-stroke was reduced in the core of the insult with all treatment protocols." (PMID 22920191, 2012). "We previously observed that MIF-KO mice show a similar CD68 immunoreactivity, but a higher Gal-3 immunoreactivity within the injured brain hemisphere 7 days following experimental stroke, in comparison to WT littermates." (PMID 21714902, 2011). "This was the case in young and old mice of each gender and increased co-localization of GFAP and CD68 with pSmad2 corresponded with the profile of increased TGFβ signaling after stroke we observed by real time imaging." (PMID 20937129, 2010). "We found that TGF-β1 predominantly co-localized with CD68, a marker of activated microglia and macrophages, indicating that they are likely to be the cells that produce it after stroke." (PMID 20937129, 2010). "Astrocytes and CD68+ innate immune cells are the cell types that respond to increased levels of TGFβ after stroke and they do so during the first week after stroke, coincident with glial scar formation." (PMID 20937129, 2010). "We found that co-localization of CD68 with pSmad2 increased in parallel with TGFβ signaling reporter gene expression after stroke." (PMID 20937129, 2010). "There were more CD68+ cells in old brains than young brains before stroke (p=0.030), which may contribute to the heightened post-stroke inflammatory response." (PMID 40661422, 2025). "Altogether, these results showed that STING inhibition by H151 could reduce the number of CD68-positive microglia, restore microglia morphology to a more ramified state, and suppress neuroinflammation after stroke." (PMID 38584255, 2024). "Collectively, these results suggest that ischemia-induced endogenous Nrf2/HO-1 axis activation in MG may play an essential role in modulating MG phenotypes through regulating CD206 and CD68 expression in MG after stroke." (PMID 39469715, 2024). "Previous work showed that mCRP was deposited in the cortical microvessels of individuals who died from either stroke or AD, and this was concomitant with expression of inflammatory markers, such as CD68 and interleukin-1 beta (IL-1β), and also aquaporin 4, associated with lymphatic Aβ clearance." (PMID 38899254, 2024). "At 3 days after photothrombotic stroke in rats, most CD68-positive cells are microglia." (PMID 34332596, 2021). "Moreover, IRG1−/− stroke animals displayed elevated microglia activation, demonstrated with increased CD68, CD86 and Iba1 expression." (PMID 34557667, 2021). "Importantly, rhFGF21 intervention significantly reversed the elevated CD68 expression, most strongly at 3 days and 7 days after stroke." (PMID 32867781, 2020). "Furthermore, the expression of CD68 was significantly upregulated beginning at 1 day following the ischemic event and continuing until 7 days post-stroke." (PMID 32867781, 2020). "The BF+stroke mice also had more CD68+ cells than stroke mice (p = 0.035)." (PMID 33187248, 2020). "This raises the possibility that CD68-positive cells might have effects that limit recovery following stroke." (PMID 30626393, 2019).
Stroke (continued). "In one study, OPN colocalized with CD68-positive myeloid cells in vessels with an impaired BBB in stroke-prone spontaneously hypertensive rats, indicating OPN-expressing microglia or macrophages may be involved in regulating BBB homeostasis." (PMID 31426806, 2019). "We further showed that CD8 expression in the post-stroke brain was associated with activated (CD68+) macrophages and that progressive accumulation of CD8+CD68+ cells in the post-stroke brain coincided with increased iNOS (M1 marker) and reduced Arg1 (M2 marker) expression on these cells." (PMID 29342151, 2018). "Immunostaining revealed a substantial reduction in CD3e+ T-lymphocyte, B220+ B-lymphocyte, and CD68+ macrophage/microglia infiltration at 24 weeks following stroke compared to eight weeks following stroke, and trichrome staining demonstrated a concurrent increase in collagen scarring." (PMID 30417081, 2018). "Nonetheless, we observed fewer CD206+ and CD68+ cells after stroke in KO mice." (PMID 28769762, 2017). "Analysis of post-mortem brain tissue from human subject who suffered two stroke events, referred as recent and old stroke, revealed that expression of cleaved caspase-8 and -3 in CD68-positive cells could only be found in the recent stroke area." (PMID 27566702, 2016). "However, in the sub-acute phase (7 d reperfusion) following stroke, TREM2-KO mice showed a decreased transcription of pro-inflammatory cytokines TNFα, IL-1α and IL-1β, associated with a reduced microglial activity (CD68, Iba1)." (PMID 23301011, 2013). "Macrophages (CD68+) are seen mostly within the center of stroke as well as at IBZ." (PMID 23217090, 2012). "We conclude that reduced sensitivity for microglial activation may indeed explain the reduced expression of CD68 in SHRs using the Et-1 model for stroke." (PMID 22647642, 2012). "Indeed, CD-68 expression is significantly increased in hypothermic rats at 3 days after the Et-1-induced stroke." (PMID 21627837, 2011). "CD68 and neurofilament immunohistochemistry and Klüver-Barrera staining were applied to assess microglial activation and axonal and myelin degeneration, respectively, and statistical methods were used to investigate the relationship between microglial density, stroke type, and survival time." (PMID 40867195, 2025). "Transcriptome, protein, and histological analyses all show that old mice have more inflammatory cells, such as CD68+ and GFAP+, than young mice before and after stroke injury, which may cause excessive elimination of synapses and post-stroke memory dysfunction." (PMID 40661422, 2025). "In this study, we found that old mice developed long-lasting memory dysfunction, which was also associated with more CD68+ activated microglia/macrophages and GFAP+ reactive astrocytes in the peri-atrophic regions and hippocampi than young stroke-only mice at 8 weeks after stroke injury (& 9)." (PMID 40661422, 2025). "The old mice had more activated microglia/macrophages (CD68+) and reactive astrocytes (GFAP+) in the peri-atrophic and hippocampal regions ipsilateral to stroke injuries than young stroke mice." (PMID 40661422, 2025). "PHA treatment also reduced CD68+/SYP+ on both sides of the hippocampi (p<0.001) and GFAP+/SYP+ cells in the hippocampi ipsilateral to stroke injury (p<0.001)." (PMID 40661422, 2025). "More synapses were engulfed by CD68+ microglia/macrophages and GFAP+ reactive astrocytes in the peri-atrophic regions and hippocampi of old stroke mice than young stroke-only mice." (PMID 40661422, 2025). "At the molecular level, we observed that diminished Nrf2/HO-1 axis activation in MG resulted in increased CD68/IL-1β and suppressed CD206 expression in MG, leading to the elevated inflammatory MG in MG-specific Nrf2 knockdown stroke mice." (PMID 39469715, 2024). "Gene floxed females showed more robust expression of CD68 in microglia, elevated brain and plasma levels of IL-1β or TNF-α, after stroke." (PMID 39399684, 2024).
Stroke (continued). "We first noted greater total densities of CD68+ and TREM2+ cells per mm2 in the frontal WM compared to the overlying cortex across the stroke cases and controls (p = 0.001)." (PMID 35748290, 2022). "There were more CD68+ cells in the hippocampal CA1 region of mice that had both BF and ischemic stroke injuries than mice that had BF or stroke alone." (PMID 33187248, 2020). "In the animal model of stroke, when PK2 was delivered into the lateral ventricle post-stroke, CD68+ cells were significantly increased." (PMID 31474981, 2019). "Analysing the thalamic area we observed extensive microgliosis at 15 days post stroke in both stroke and LOPC groups, while at 30 days microglia activation was significantly decreased in LOPC treated (Iba1 p < 0.01, CD68 p < 0.01, CD11b p < 0.05)." (PMID 30890719, 2019). "Instead in the PO area, only LOPC treatment was found giving a significant contribution (p < 0.05), with a significant difference between stroke and LOPC at 30 days for both Iba1 and CD68 (p < 0.05) as assessed by post-hoc analysis." (PMID 30890719, 2019). "In contrast to 7 days, at 14 days after stroke there was an increase of CD45 and CD68-positive M/Ms in the peri-infarct area of miR-155 inhibited mice." (PMID 29527155, 2018). "Following the premise that CD8 is involved in M1 polarization in stroke, we further studied the evolution of the M1/M2 markers on CD8+CD68+ cells." (PMID 29342151, 2018). "CD68+ activated microglia and macrophages were the predominant source of increased TGF-β1 after stroke and astrocytes and CD68+ cells were the main cell types that responded to the post-stroke increase in TGF-β1." (PMID 20937129, 2010). "We found that PHA treatment reduced GFAP+ astrocytes (p=0.016) in the hippocampi ipsilateral to stroke injury but not CD68+ microglia/macrophages." (PMID 40661422, 2025). "Moreover, we identified attenuated Nrf2/HO-1 axis activation led to increased CD68/IL-1β and suppressed CD206 expression in MG, resulting in aggravated inflammatory MG in MG-specific Nrf2 knockdown mice after stroke." (PMID 39469715, 2024). "However, in the 2 weeks post-stroke samples, high numbers of MANF and CD68 positive round cells were detected in the infarct region." (PMID 38229173, 2024). "Interestingly, our data showed that stroke in HFD mice upregulates the expression of a surrogate marker of activation Ly6C and the co-stimulatory receptor CD68 on blood MΦ." (PMID 39845972, 2024). "At these later times, Cd68-postive, P2yr12-negative cells were present in NPC grafted lesions, but these cells were at a visibly lower density compared to the untreated stroke suggesting an NPC graft induced shift in the immune cell milieu within the lesion core." (PMID 36171203, 2022). "We have shown that Arg1-positive (arginase 1) and phagocytic CD68-positive cells are increased after viral vector-mediated MANF gene delivery in a rat dMCAo cortical ischemic stroke model, coinciding with elevated brain repair processes after stroke." (PMID 35783104, 2022). "In the lateral CC, which was more distant from the primary occlusion site, we again observed a stroke-induced increase in CD68 expression, an effect that was significantly lower in the stroke + CORT group (sham = 5.713% vs. stroke = 21.24%, p < 0.05, stroke vs. stroke + CORT = 4.961%, p < 0.05)." (PMID 34206635, 2021). "Moreover, we further detected the temporal profiles when infiltrating immune cells defined as CD45high cells, macrophages, and CD68+, CD86+, and CD206+ macrophages were present in the ischemic brain at 1, 3, and 7 days following stroke." (PMID 32867781, 2020). "The percentage area covered by CD68+ cells in the stroke border or peri-infarct cortex was not different between Adrb2cKO and Adrb2WT mice." (PMID 31138227, 2019).
Stroke (continued). "We focused on such factors, i.e. IL-6, CD68, CCL3 and CCL5, which have already been described by us and others occurring in the ischemic peri-infarct area and being relevant for tMCAO-induced brain damage and post-stroke therapy." (PMID 24024100, 2013). "The results showed that no positive staining was detected in non-ischemic brain, but CD68-positive cells were increased in both ischemic brains of WT and nude rats 72 h post-stroke." (PMID 23555048, 2013). "DC infusion 3 hours post-tMCAO did not affect infarct size or recruitment of CD68-positive immune cells at 24 hours, suggesting that DC treatment did not significantly alter the initial innate immune response to stroke injury within this time frame." (PMID 23613937, 2013). "In addition, stroke led to an increased expression of the activation markers Ly6C and CD68 on monocyte/macrophages (MΦ) in HFD mice but not in ND mice." (PMID 39845972, 2024). "CD68 expression in the CST: In the dorsal-most region of the CST, stroke significantly increased the intensity of CD68 expression, and this effect was significantly reduced in the stroke + CORT group (sham = 2.703% vs. stroke = 21.96%, p < 0.01; stroke vs. stroke + CORT = 5.223%, p < 0.01)." (PMID 34206635, 2021). "However, at 3 days post-stroke, we did not identify the cellular source of changes in inflammatory gene expression or distinguish between microglia or MDMs in the brain, since CD68 and Iba1 are markers known to label both cell types." (PMID 31138227, 2019). "We could not detect PARP cleavage in CD68 positive cells either in the ischemic core or peri-infarct area after stroke, indicating that the caspase activation in these cells is not linked to cell death." (PMID 27566702, 2016). "Similarly, stroke increased the expression of CD68 but not Ly6C on splenic MΦ in HFD mice." (PMID 39845972, 2024).